NR4A1 (nuclear receptor subfamily 4 group A member 1)
Diseases named in the same sentence as NR4A1 in open-access papers (continued):
Sharing a sentence is not in itself a finding about the gene and the disease.
Hyperglycemia (13 papers, 2013 to 2025). An increased concentration of glucose in the blood. "For example, metformin may prevent the endothelial dysfunction caused by hyperglycemia-related oxidative stress through Nr4a1." (PMID 35139776, 2022). "Nr4a1 is one of the nuclear receptors and is reported to be upregulated in mice podocytes in hyperglycemia." (PMID 38132237, 2023). "Nuclear receptor subfamily 4 group A member 1 (NR4A1) is activated in response to hyperglycemia and contributes to the pathogenesis of diabetic nephropathy." (PMID 34067150, 2021). "Moreover, metformin’s ability to ameliorate hyperglycemia-induced endothelial dysfunction by modulating NR4a168, suggests a close relationship between NR4a1 and vascular development." (PMID 38834564, 2024).
Hypertension (12 papers, 2012 to 2025). The presence of chronic increased pressure in the systemic arterial system. "There were several genes affected by high-intensity interval training during HFD hypertension, which were Trim39, Nr4a1, Plekhf1, Tgm2, Lgals1, Egr1, and Atf3." (PMID 41516177, 2025). "Therefore, we speculated that NR4A1 may be a potential target for acupuncture treatment of hypertension, and acupuncture may achieve this by inhibiting central neuroinflammation." (PMID 39234603, 2024). "In the context of hypertension, the absence of NR4A1 aggravates renal injury." (PMID 40461634, 2025).
osteoporosis (12 papers, 2020 to 2026). A condition of reduced bone mass, with decreased cortical thickness and a decrease in the number and size of the trabeculae of cancellous bone (but normal chemical composition), resulting in increased fracture incidence. "The NR4A1 mRNA expression level in the BMSCs of postmenopausal osteoporosis patients was reported to be significantly higher than that in the normal control group, suggesting that NR4A1 may be related to osteogenesis." (PMID 33204710, 2020).
Parkinson disease (12 papers, 2013 to 2025). A progressive degenerative disorder of the central nervous system characterized by loss of dopamine producing neurons in the substantia nigra and the presence of Lewy bodies in the substantia nigra and locus coeruleus. "In mice injected with α-synuclein preformed fibrils, a widely used model of Parkinson's disease, NR4A1 translocates to mitochondria and reduces the loss of dopamine neurons." (PMID 40746844, 2025). "PC12 rat adrenal pheochromocytoma cells were used as a model of Parkinson’s disease for investigating the role of NR4A1 in modulating the effects of MPP+-induced inflammation (and oxidative stress) and induction of TNFα, MCP-1, IL-6, and NFkB." (PMID 40871737, 2025). "Nr4a1 also regulates spine density in the striatum, which impacts Parkinson’s disease and addiction phenotypes." (PMID 31541002, 2019). "In the mouse brain, NR4A1 protects dopaminergic neurons in a rodent model of Parkinson’s disease and delays the onset of clinical symptoms of experimental autoimmune encephalomyelitis (EAE) by inhibiting microglial activation and proinflammatory gene expression." (PMID 37486903, 2023). "In addition, NR4A1 regulates mTOR signaling in angiotensinαII-induced cardiac hypertrophy; NR4A1 also enhances muscle mass in mice through IGF1-induced activation of mTOR, and in a mouse model of Parkinson’s disease the anti-inflammatory effect of NR4A1 is also associated with NRF2." (PMID 40871737, 2025). "Thus, NR4A1 might have a protective role in Parkinson's disease." (PMID 40746844, 2025). "In a model of Parkinson’s disease, 1-methyl-4-phenylpyridinium (MMP+)-induced apoptosis and ROS in SH-SY5Y cells was inhibited by overexpression of YY1, which in turn induced NR4A1 expression." (PMID 40871737, 2025).
rhabdomyosarcoma (11 papers, 2016 to 2025). A rare aggressive malignant mesenchymal neoplasm arising from skeletal muscle. "NR4A1 has been found to be overexpressed in a spectrum of solid tumors, such as breast, pancreatic, ovarian, colon, endometrial, and rhabdomyosarcomas." (PMID 40361912, 2025). "Using NR4A1-responsive rhabdomyosarcoma Rh30 cellsas a model, PFOS induced NR4A1-dependent cell proliferation and Rh30cell migration and invasion." (PMID 40066943, 2025). "Initial studies showed that both quercetin and kaempferol bound NR4A1 and in vitro studies confirmed that both compounds exhibited inverse NR4A1 agonist activities in rhabdomyosarcoma cells and inhibited tumor growth in an athymic mouse xenograft model." (PMID 38116863, 2024). "Previous studies showed that quercetin and kaempferol acted as NR4A1 antagonists in Rh30 rhabdomyosarcoma cells and decreased NR4A1-dependent transactivation in this cell line." (PMID 37175855, 2023). "Kaempferol and quercetin are ligands that bind NR4A1 and exhibit NR4A1 antagonist activities in Rh30 rhabdomyosarcoma cells and this has previously been observed for other NR4A1 antagonist such as the bis-indole derived compounds that also bind NR4A1." (PMID 37175855, 2023). "In rhabdomyosarcoma, they can inhibit NR4A1-dependent reverse transcription activation and downstream target genes and inhibit the growth of xenograft rhabdomyosarcoma in nude mice." (PMID 37497415, 2023). "The activities of kaempferol and quercetin were determined in direct binding to NR4A1 protein and in NR4A1-dependent transactivation assays in Rh30 and Rh41 rhabdomyosarcoma (RMS) cells." (PMID 34906197, 2021). "Studies in this laboratory have been investigating the pro-oncogenic roles of the nuclear orphan receptor 4A1 (NR4A1, Nur77) in rhabdomyosarcoma (RMS) and other cancer cell lines." (PMID 34906197, 2021). "The orphan nuclear receptor NR4A1 is expressed in tumors from rhabdomyosarcoma (RMS) patients and Rh30 and RD RMS cell lines, and we used RNA interference (RNAi) to investigate the role of this receptor in RMS cells." (PMID 27144436, 2016). "In contrast, NR4A1/Sp4 regulated β1-integrin and the oncogenic PAX3-FOX01 fusion gene expression in rhabdomyosarcoma cells, whereas NR4A1/Sp1 regulated G9a expression in the same cell lines." (PMID 39858066, 2025). "For example, the PAX3-FOX01 fusion gene is oncogenic and a major driver of alveolar rhabdomyosarcoma (ARMS) tumor growth in children and in mouse models and DIM8 inhibits NR4A1-regulated PAX3-FOX01 and downstream genes in ARMS cells and in animal models." (PMID 38116863, 2024).
thyroid cancer (11 papers, 2012 to 2025). "We found that DPP4, TIMP1 and TYRO3 were associated with a better prognosis and survival in patients with thyroid cancer, while FABP4, NR4A1 and SNCA were associated with a poor prognosis and survival in patients with thyroid cancer." (PMID 36407322, 2022). "We focused on the effect of IMCA on thyroid cancer cell viability, apoptosis, nuclear export of NR4A1, and cell proliferation regulated by the mTOR pathway." (PMID 29498706, 2018). "The effect of NR4A1 on the growth and survival was investigated using the short-interfering RNA (siRNA) method in thyroid cancer cell lines." (PMID 29498706, 2018). "NR4A1 also regulates the pro-survival genes and pathways in many cancer cells, including thyroid carcinoma cells." (PMID 29498706, 2018). "Our findings uncover an oncogenic function for NR4A1 in the papillary histotype of thyroid cancer." (PMID 35110542, 2022). "We investigated the function of NR4A1 in thyroid cancer cell lines using RNAi." (PMID 29498706, 2018). "The cell survival was significantly inhibited in thyroid cancer cell with low expression of NR4A1." (PMID 29498706, 2018). "Immunofluorescence assays showed that IMCA induced NR4A1 translocation from the nucleus to the cytoplasm in thyroid cancer cell lines, which may be involved in the cell apoptotic process." (PMID 29498706, 2018). "Thus, IMCA inhibits nuclear NR4A1-mediated mTOR pathways and represent a new class of mechanism-based drugs for thyroid carcinoma chemotherapy." (PMID 29498706, 2018). "It is thought that IMCA may be a specific antagonist of NR4A1 through the NR4A1 and SESN/AMPK/mTOR signaling pathway and therefore can be used in the treatment of thyroid carcinomas." (PMID 40956676, 2025).
type 2 diabetes (11 papers, 2010 to 2026). "NR4A1 significantly enriched the pathways associated with “glycosphingolipid biosynthesis,” “circadian rhythms,” and “type 2 diabetes”." (PMID 38263097, 2024). "Nr4a1 has been widely studied in different disease models ranging from cancer to metabolic diseases such as type 2 diabetes." (PMID 39644367, 2024). "Sabaratnam observed that exercise induces the release of NR4A1, modulating the immune responses in people with type-2 diabetes." (PMID 34067297, 2021). "The expression of NR4A1 in skeletal muscle significantly enhances mitochondrial function in type 2 diabetes." (PMID 30013988, 2018). "Together, these findings indicate that loss of Lcn10 skews macrophage polarization to pro-inflammatory phenotype and aggravates cardiac dysfunction during type-2 diabetes through the disruption of Nr4a1-mediated anti-inflammatory signaling pathway in macrophages." (PMID 35757735, 2022).
glioma (10 papers, 2014 to 2025). A benign or malignant brain and spinal cord tumor that arises from glial cells (astrocytes, oligodendrocytes, ependymal cells). "However, PDGF-BB-driven soft agar colony formation of NIH3T3 and glioma cells was strongly enhanced by NR4A1 expression." (PMID 25269081, 2014). "PE‐Sun, which consists of three pathway‐extended genes, SIAE, NR4A1 and EPHA2, was evaluated in gliomas." (PMID 34766125, 2020). "Our findings suggest that NR4A1 may regulate the protein expression of SERPINE1 by binding to it, and that inhibiting SERPINE1 can downregulate the invasion and infiltrative spread of glioma primary cells." (PMID 41584614, 2025).
liver cancer (10 papers, 2017 to 2025). An epithelial or non-epithelial malignant neoplasm that arises from the liver. "A class of Bisindole-derived (CDIMs) NR4A1 antagonists, such as 1,1-bis(3’-indolyl)-1-(p-hydroxyphenyl) methane (DIM-C-pPhOH), can decrease the expression of NR4A1 in breast, lung, and liver cancer cells to inhibit tumor growth, EMT and stemness." (PMID 36052242, 2022). "Consistently, NR4A1 expression can mediate bile acid-induced cell growth in human colon and liver cancer cells by modulating the expression of survival genes." (PMID 35110542, 2022). "Lastly, we investigated the pathways that might be involved in NR4A1 induction under TRAIL treatment in liver cancer cells." (PMID 30821058, 2019). "However in TRAIL‐resistant liver cancer cells, TRAIL‐induced NR4A1 expression through NF‐κB activation may attenuate its death induction effect." (PMID 30821058, 2019).
Autoimmunity (9 papers, 2015 to 2025). The occurrence of an immune reaction against the organism's own cells or tissues. "Similarly, Nr4a1 expression in T cells has been shown to suppress inflammation associated with autoimmunity and cancer." (PMID 40114913, 2025). "As a consequence suppressing NR4A1 expression promotes autoimmunity while deletion of NR4A2 protects from Th17-mediated autoimmune diseases." (PMID 33597928, 2020). "NR4A1 deficiency impairs regulatory T cell function and promotes inflammatory T cell activation, exacerbating autoimmunity and contributing to SLE pathogenesis, and neuronal restoration of NR4A1 protects against synaptic loss and neuropsychiatric symptoms in lupus-prone mice." (PMID 41438090, 2025). "We did not, however, observe evidence of pathologic autoimmunity in these animals at one year of age (data not shown), suggesting that additional factors compensate for the loss of Nr4a1 to prevent autoimmunity." (PMID 26091486, 2015). "However this is in slight contradiction with the fact that autoimmunity and reduced lifespan was observed in Nr4a1/Nr4a3 but not in Nr4a2/Nr4a3 double deficient mice." (PMID 33597928, 2020). "While this may indicate the importance of NR4A1/NR4A3 in clonal deletion, the cause of autoimmunity in this model is unclear, especially since these HDAC7 mutants demonstrated a generalized suppressive impact on the negative selection transcriptional program and impaired generation of Tregs." (PMID 33597928, 2020). "Molecules that specifically inhibit Nr4a1 and Nr4a2, but not Nr4a3, are also candidates for tumor Treg-specific inhibitors, as Foxp3CreNr4a-DcKO mice do not develop autoimmunity but the mice do develop augmented antitumor immunity." (PMID 35514961, 2022). "In addition to neuron, a lack of Nr4a1 in both thymus and peripheral T cells has been reported to exacerbate autoimmunity through inhibition of regulatory T cells and activation of inflammatory T cells, which may contribute to SLE." (PMID 35177587, 2022).
cardiac hypertrophy (9 papers, 2015 to 2025). "In cardiomyocytes, Nr4a1 was found to block proliferation induced by neuropeptide Y which has been linked to cardiac hypertrophy." (PMID 31683815, 2019). "Together, Nr4a1 and Nr4a2 protect against cardiac hypertrophy and vessel narrowing due to stress and other causes such as atherosclerosis." (PMID 31683815, 2019). "NR4A1 reportedly participates in myocardial diseases through various mechanisms, including cardiomyocyte apoptosis, cardiac hypertrophy and inflammation." (PMID 31443660, 2019). "Likewise, adenovector-mediated cardiac overexpression of NR4A1 in mice inhibited isoproterenol-induced cardiac hypertrophy." (PMID 35625658, 2022).
depression (9 papers, 2014 to 2026). "Through the PPI network we found that the potential targets of ZZCD for the treatment of anxiety and depression are Fos, Nr4a1, Dusp1, Junb, and Egr2." (PMID 37905694, 2024). "Notable downregulated genes matching depression were: BDNF, the glucocorticoid receptor, NR3C1, and activity related genes, EGR1, FOS, NR4A1, FOSB, and ARC." (PMID 34997033, 2022). "Some of the common down genes in maternal C57 mice and depression were for the MAP kinase pathway and some of the common down genes included: FOS, EGR1, DUSP1, BDNF, NR4A1, NR3C1, the neuropeptide somatostatin (SST), and one of the its receptors, SSTR2." (PMID 34997033, 2022). "In most of the top models, a consistent dysregulation of MAP kinase pathway was identified and the genes NR4A1, BDNF, ARC, EGR2, and PDE7B were consistently downregulated as in humans with depression." (PMID 34997033, 2022). "The analysis of mRNA expression in the prefrontal cortex of suicide victims with major depressive disorder revealed a differential profile with 27 downregulated mRNAs, including HSPA1A, HSPA1B, DNAJB1, NR4A1, and GADD45B, which are involved in proteostasis, transcriptional regulation, and apoptosis." (PMID 41977312, 2026).
glioblastoma (9 papers, 2014 to 2025). The most malignant astrocytic tumor (WHO grade IV). "This is consistent with the observation that in different tumor types, including glioblastoma, migration and invasion are associated with Erk1/2 activation and NR4A1 expression." (PMID 25269081, 2014). "Consistent with the observation that NR4A1 is overexpressed in tumor cells, we show that NR4A1 expression is essential for glioblastoma cell colony formation in soft agar." (PMID 25269081, 2014). "A strong enhancement of PDGF-BB stimulated colony growth was seen by overexpression of NR4A1 also in the glioblastoma cell line U-251MG and U-105MG exhibits a similar trend." (PMID 25269081, 2014). "Moreover, dual NR4A1/NR4A2 regulation of TWIST1 in glioblastoma cells has also recently been reported using a similar approach." (PMID 40332813, 2025). "NR4A1 is essential for colony formation of glioblastoma cells on soft agar." (PMID 34766125, 2020). "This study clarifies the regulation of NR4A1 in NIH3T3 and demonstrates its role in PDGF-BB-meditated cell transformation both in NIH3T3 and in glioblastoma-derived cell lines; our findings suggest that NR4A1 may be a target in cancer treatment." (PMID 25269081, 2014). "In summary, results of this study demonstrate that DIM-3,5 and DIM8-3,5 analogs bind both NR4A1 and NR4A2, activate NR4A1- and NR4A2-dependent transactivation, and, like other DIM analogs, these compounds are cytotoxic to colon and glioblastoma cells." (PMID 38540704, 2024). "Regulation of NR4A1 and TNC expression in glioblastomas remains unreported; however, TNC is an ECM receptor protein that involves ECM receptor interactions." (PMID 35327982, 2022). "Moreover, the DIM-3,5 and DIM8-3,5 analogs also decreased NR4A1- and NR4A2-dependent transactivation in U87G glioblastoma cells transfected with GAL4-NR4A1 or GAL4-NR4A2 chimeras and a UAS-luciferase reporter gene construct." (PMID 38540704, 2024). "Moreover, overexpression of NR4A1 promoted anchorage-independent growth of NIH3T3 cells and the glioblastoma cell lines U-105MG and U-251MG." (PMID 25269081, 2014).
schizophrenia (9 papers, 2014 to 2024). A major psychotic disorder characterized by abnormalities in the perception or expression of reality. "Functions ascribed to NR4A1 in neuronal differentiation and neurite outgrowth, learning and memory and immunity are all potentially relevant to schizophrenia." (PMID 27992436, 2016). "In this analysis, the most significant differentially expressed gene was the nuclear receptor NR4A1 (Nur77), for which expression is reduced in schizophrenia (54%, p<0.01, FDR<0.1)." (PMID 27992436, 2016). "Key priorities should perhaps be nuclear receptor 4A1 (NR4A1) activators given that Nr4a1 down-regulation in isolates was greatest in terms of fold-change, and it was included in the 13% of DEGs shared with three of the four selected illnesses (namely schizophrenia, MDD and BP)." (PMID 39502833, 2024). "There are also agonists or activators for products of six DEGs that are down-regulated in ASD (Lrrk2), schizophrenia (Chrm4, Prkca), schizophrenia and BP (Klf2) or schizophrenia, BP and MDD (Nr4a1 and Nr4a3)." (PMID 39502833, 2024). "This study presents evidence for down-regulation of the nuclear receptors NR4A1, NR4A2, RXRB, and KLF4 mRNAs in the DLPFC in schizophrenia and evidence of reduced RARG and RXRG expression in females with schizophrenia." (PMID 27992436, 2016). "We found significantly down regulated expression of NR4A1 (Nurr 77) and KLF4 mRNAs in people with schizophrenia compared to controls, by both NGS and qPCR (p = or <0.01)." (PMID 27992436, 2016). "This study reports significant changes in the nuclear receptors NR4A1, NR4A2, and RXRB and KLF4 in schizophrenia and provides further evidence of a role for the nuclear receptors in the disease process." (PMID 27992436, 2016). "We confirmed the edgeR results using a different analysis program, DESeq2, which also found NR4A1 and KLF4 as the most significantly differentially expressed genes with decreases in schizophrenia similar to that found with edgeR (51% and 47%, respectively)." (PMID 27992436, 2016).